SECISBP2 (SECIS binding protein 2)
Description:
mRNA-binding protein that binds to the SECIS (selenocysteine insertion sequence) element present in the 3'-UTR of mRNAs encoding selenoproteins and facilitates the incorporation of the rare amino acid selenocysteine. Insertion of selenocysteine at UGA codons is mediated by SECISBP2 and EEFSEC: SECISBP2 (1) specifically binds the SECIS sequence once the 80S ribosome encounters an in-frame UGA codon and (2) contacts the RPS27A/eS31 of the 40S ribosome before ribosome stalling. (3) GTP-bound EEFSEC then delivers selenocysteinyl-tRNA(Sec) to the 80S ribosome and adopts a preaccommodated state conformation. (4) After GTP hydrolysis, EEFSEC dissociates from the assembly, selenocysteinyl-tRNA(Sec) accommodates, and peptide bond synthesis and selenoprotein elongation occur.
Synonyms: SBP2; THMA1
Tractability: Small molecule: a structure with a bound ligand is known. PROTAC: ubiquitination databases record sites on it.
Gene: Protein-coding gene on chromosome 9 (89,318,460 to 89,363,633, forward strand). Ensembl gene ENSG00000187742.
Subcellular location: Nucleus (Isoform 1); Mitochondrion (Isoform 2)
Subcellular location (Human Protein Atlas): Nucleoplasm
Pathways (Reactome):
Metabolism: Selenocysteine synthesis
Gene Ontology:
Molecular function: DNA binding; mRNA 3'-UTR binding; protein binding; RNA binding; selenocysteine insertion sequence binding; ribonucleoprotein complex binding
Biological process: selenocysteine incorporation; selenium compound metabolic process
Cellular component: nucleoplasm; mitochondrion; ribonucleoprotein complex; cytosol; nucleus
Genetic constraint (gnomAD): Loss-of-function variants: 92 observed, 91.35 expected, observed/expected ratio (o/e) 1.01, 90% interval 0.85 to 1.2. The upper end of that interval is the gene's LOEUF score, 1.2, which puts it in group 5 of 6, group 1 being the genes least tolerant of losing a copy. Missense variants: 993 observed, 1,016.6 expected, observed/expected ratio (o/e) 0.98, 90% interval 0.93 to 1.03. Synonymous variants: 385 observed, 369.62 expected, observed/expected ratio (o/e) 1.04, 90% interval 0.96 to 1.13.
Homologues: Orthologues: chimpanzee SECISBP2 (99% identical), macaque SECISBP2 (97% identical), pig SECISBP2 (79% identical), rabbit SECISBP2 (79% identical), guinea pig SECISBP2 (75% identical), mouse Secisbp2 (72% identical), rat Secisbp2 (72% identical), dog SECISBP2 (68% identical), tropical clawed frog secisbp2 (34% identical), zebrafish secisbp2 (28% identical), Drosophila melanogaster Sbp2 (11% identical). Paralogues in human: SECISBP2L (29% identical).
Diseases named in the same sentence as SECISBP2 in open-access papers:
SECISBP2 is named in the same sentence as 39 diseases in open-access papers, as found by Europe PMC text mining. Sharing a sentence is not in itself a finding about the gene and the disease. The quoted sentences say what the papers report.
developmental delay (4 papers, 2023 to 2025). "It is essential to include SECISBP2 in gene panels for thyroid dysfunction and developmental delay to avoid diagnostic delays and inappropriate treatment." (PMID 40918659, 2025). "In humans, carriers of mutations in these genes (including SECISBP2, TRU-TCA1-1, and SEPSECS) display the severe multisystem phenotypes of global developmental delay with features of myopathy and cerebellar and optic atrophy." (PMID 37108730, 2023).
Azoospermia (3 papers, 2015 to 2022). Absence of any measurable level of sperm,whereby spermatozoa cannot be observed even after centrifugation of the semen pellet. "Individuals with SECISBP2 defects exhibit a multisystem phenotype including growth retardation, fatigue and muscle weakness, sensorineural hearing loss, increased whole body fat mass, azoospermia and cutaneous photosensitivity." (PMID 34884733, 2021).
congenital hypothyroidism (2 papers, 2022 to 2024). A thyroid hormone deficiency present from birth. "Thyroid hormone resistance due to MCT8, THRα, and SECISBP2 defects may lead to a severe developmental delay like congenital hypothyroidism, but is characterized by normal TSH and partially normal T3 and T4 levels." (PMID 39201272, 2024).
aneurysm (1 paper, 2023). Bulging or ballooning in an area of an artery secondary to arterial wall weakening. "We observed similar survival, aneurysm formation, oxidative damage and VSMC apoptosis in thoracic aortae of wild-type and heterozygous, VSMC-specific Secisbp2 knockout mice, suggesting that the product of a single Secisbp2 allele mediates sufficient selenoprotein synthesis to prevent TAAs." (PMID 38042913, 2023).
cerebral palsy (1 paper, 2024). A group of disorders affecting the development of movement and posture, often accompanied by disturbances of sensation, perception, cognition, and behavior. "Next, we tested the percentiles for the fT3/fT4 ratio for their discriminatory power between pathologies that are either thyroid-related (e.g., in patients with mutations in THRA, SLC16A2, or SECISBP2) or not (e.g., in patients with cerebral palsy)." (PMID 39201272, 2024).
congenital myopathy (1 paper, 2025). "This same mutation was observed in a Brazilian girl with delayed bone age, congenital myopathy, and neurological impairment who carried compound heterozygous SECISBP2 mutations." (PMID 40918659, 2025).
diffuse large B-cell lymphoma (1 paper, 2022). "Our data are consistent with a recent report, in which GPX4 and TXNRD1 were still expressed in diffuse large B-cell lymphoma cell lines apparently deficient in SECISBP2 immunostaining, although it was not further studied what kind of mutations may have caused the lack of SECISBP2 protein." (PMID 36291713, 2022).
hypothyroidism (1 paper, 2023). Abnormally low levels of thyroid hormone. "This notion accords with the characterization of subjects with inherited mutations in selenoprotein biosynthesis with impaired DIO biosynthesis (SECISBP2 mutations), where TSH was unaltered, whereas the T3 to T4 ratio was reduced and intracellular hypothyroidism was present." (PMID 37423160, 2023).
Insulin resistance (1 paper, 2020). Increased resistance towards insulin, that is, diminished effectiveness of insulin in reducing blood glucose levels. "It is also noteworthy that suppression of SECISBP2 in adipose tissue macrophages induces M1 phenotype activation, proinflammatory signaling with subsequent adipose tissue infiltration and inflammation, as well as its hypertrophy and insulin resistance." (PMID 32344656, 2020). "A case report series has demonstrated that SECISBP2 mutations are associated with increased body fat mass, although metabolic profile including insulin resistance was not affected." (PMID 32344656, 2020).
lymphoma (1 paper, 2022). A malignant (clonal) proliferation of B- lymphocytes or T- lymphocytes which involves the lymph nodes, bone marrow and/or extranodal sites. "Further, the downstream regulator of GPX4, i.e., SECISBP2 (Selenocysteine Insertion Sequence-Binding Protein 2), which regulates various selenoproteins, was revealed as a novel prognostic predictor of DLBC lymphomas and may serve as a potential therapeutic target." (PMID 35887320, 2022).
Obesity (1 paper, 2021). Accumulation of substantial excess body fat. "On the other hand, people with rare mutations of the SECISBP2 gene leading to SECISBP2 deficiency developed growth retardation with thyroid hormone abnormalities, including a 12-year-old Brazilian girl with a nonsense mutation that also presented a strong obesity phenotype." (PMID 34204631, 2021).
cancer (2 papers, 2015 to 2024). A tumor composed of atypical neoplastic, often pleomorphic cells that invade other tissues. "Among the most significantly downregulated genes in tumor samples were AGBL5, SECISBP2, and PLTP, which are involved in protein deglutamylation, selenoprotein synthesis, and lipid metabolism, respectively, and their downregulation may impact platelet function and stability in cancer." (PMID 39001461, 2024).
neurodevelopmental disorder (1 paper, 2025). A behavioral and cognitive disorder with onset during the developmental period that involves impaired or aberrant development of intellectual, motor, or social functions. "This case highlights the importance of identifying the specific biochemical profile associated with SECISBP2 deficiency and advocates for the inclusion of SECISBP2 in genetic testing panels for endocrine and neurodevelopmental disorders to prevent diagnostic delays." (PMID 40918659, 2025).
SECISBP2 also shares sentences with these, for which no sentence is quoted: myopathy (3 papers); osteoarthritis (2); thyroid hormone resistance (2); tumor (2); Allan-Herndon-Dudley syndrome (1); autism spectrum disorder (1); babesiosis (1); cartilage disease (1); dilatation (1); endocrine disorders (1); esophageal cancer (1); gastric cancer (1); genetic disorders (1); Hepatitis (1); infection (1); liver diseases (1); liver fibrosis (1); metabolic disease (1); muscle-eye brain disease (1); nonalcoholic fatty liver disease (1); optic atrophy (1); prostate carcinoma (1); prostate tumors (1); Raynaud disease (1); selenium deficiency (1); thyroid (1).